ALB (albumin)
Diseases named in the same sentence as ALB in open-access papers (continued):
Sharing a sentence is not in itself a finding about the gene and the disease.
Sepsis (continued). "It is the largest study to date on the effect of albumin administration on kidney function in patients undergoing cardiac surgery, a clinical setting with very limited data and a different pathophysiological model of AKI than severe sepsis or shock." (PMID 25394836, 2014). "A separate multicentre study in Italy, the ALBIOS trial, recruited 1800 patients with sepsis or septic shock and compared resuscitation with 20% albumin or a crystalloid the results of which are not yet published." (PMID 25180196, 2014). "Although many of the studies included had not used proper methodology, the results suggest that albumin does not have specific adverse effects in sepsis." (PMID 25180196, 2014). "The present meta-analysis did not demonstrate significant advantages of albumin over other fluids for resuscitation in patients with sepsis of any severity." (PMID 25474401, 2014). "SAA has so far not been investigated in sepsis and associations between SAA, CRP and albumin have not been assessed in canine pyometra." (PMID 25430894, 2014). "PMVEC isolated from human lung were treated in vitro with septic stimulation (lipopolysaccharide [LPS], a mixture of clinically-relevant cytokines [cytomix], or plasma from patients with severe sepsis), and the trans-PMVEC leak of Evans Blue dye-labeled albumin assessed." (PMID 23393568, 2013). "In six of these patients, albumin concentration was stable for several weeks without any signs of sepsis." (PMID 22669399, 2012). "The factors associated with hospital mortality in univariable analysis were CD4 lymphocyte count (per 10 cells/mm3 decrease), admission diagnosis of sepsis, the interval between hospitalization and ICU transfer of more than 24 hours, and serum albumin level (per 1 g/dl decrease)." (PMID 21871086, 2011). "Similarly, in sepsis higher cardiac index and oxygenation after HES than albumin administration were observed in several trials." (PMID 18318896, 2008). "Both the severe sepsis group and the nonseptic critically ill group had similar lowered plasma albumin levels (26.4 ± 6.4 g/l versus 29.2 ± 3.9 g/l; P = 0.071)." (PMID 18706105, 2008). "While edema may pose problems in sepsis as well, this review suggested advantages of HES over albumin in sepsis, e.g., higher cardiac index and oxygenation." (PMID 18318896, 2008). "The multi-center non-randomized observational Sepsis Occurrence in Acutely ill Patients (SOAP) study also did not differentiate between types of albumin solutions." (PMID 18318896, 2008). "Patients who received albumin had the same mean age, but were more likely to have cancer or liver cirrhosis, to be a surgical admission, and to have sepsis than the patients who did not receive albumin." (PMID 16356223, 2005). "The Sepsis Occurrence in Acutely ill Patients (SOAP) study did exactly this to determine current intensive care unit (ICU) practice and the effects of that practice on outcomes for various topics, including administration of albumin." (PMID 16356223, 2005). "However, a number of studies have also found that albumin use does not significantly reduce mortality in patients with sepsis, which is consistent with our secondary outcome that albumin does not improve short-term survival." (PMID 40841985, 2025). "A study indicated that albumin may be the preferred colloid for resuscitating patients with sepsis and septic shock, although no definitive guidance is available for transitioning from crystalloid to colloid use during resuscitation." (PMID 40649163, 2025). "Compared to albumin or BUN, BAR demonstrates a stronger correlation with improved acute-phase survival rates in patients with chronic heart failure complicated by sepsis, and may offer relevant implications for both treatment protocol selection and clinical outcomes." (PMID 40104144, 2025). "However, a review of the extant literature revealed no studies directly examining the association between albumin use and the risk of SA-AKI in sepsis patients." (PMID 40841985, 2025).
Sepsis (continued). "This study aims to analyze the prognostic significance of Lactate/Albumin ratio for in-hospital complications and outcomes among patients diagnosed with Acute Respiratory failure, the prognostic significance of LAR for in-hospital complications and outcomes among patients diagnosed with sepsis." (PMID 40130722, 2025). "AUC value with 95% CI, sensitivity and specificity of lactate/albumin ratio, lactate alone and SOFA score for predicting in hospital outcomes such as mortality, need of inotropes and requirement of mechanical ventilation among patient diagnosed with both sepsis and ARF." (PMID 40130722, 2025). "Fluid resuscitation in patients with cirrhosis and hypovolemia in the central compartment from sepsis is a balancing act, and the lack of positive findings from our study concerning albumin use provides further guidance for clinicians seeking to optimize outcomes in this complex patient population." (PMID 40386509, 2025). "A sepsis and a SARS-CoV-2 infection were excluded, but a progressive multi-organ failure was observed needing non-invasive ventilation, continuous renal replacement therapy, red blood cells and platelets transfusions, and fibrinogen and albumin supplementation." (PMID 40374837, 2025). "In severe sepsis, albumin supplementation failed to improve survival (ALBIOS)." (PMID 40766965, 2025). "However, by including albumin in the assessment, the LAR provides a more comprehensive measure of physiological disturbances and the body’s response to inflammation in patients with sepsis, which are key changes during the progression of sepsis." (PMID 40046181, 2025). "As organ dysfunction is a major determinant of sepsis, the SOFA score would be an appropriate tool for determining the severity of the disease, and its prognostic ability may be enhanced when combined with albumin." (PMID 39459557, 2024). "However, another multicentre study showed that compared with crystalloids alone, ALB replacement in combination with crystalloids did not improve the survival rate at 28 or 90 days in patients with severe sepsis." (PMID 38898407, 2024). "Several recent studies have highlighted the potential prognostic markers of outcome in severe sepsis, including the central venous minus arterial carbon dioxide pressure to arterial minus central venous oxygen content ratio (Pcv-aCO2/Ca-cvO2, the CRP/albumin ratio, and lactate clearance." (PMID 38398049, 2024). "Likewise, a Turkish study has demonstrated a significant difference in the albumin levels between the survivors (albumin level=3.0 g/dL) and non-survivors (albumin level=2.6 g/dL) patients with sepsis (p=0.001)." (PMID 39539863, 2024). "Moreover, given the complexity of sepsis patients, the results of current randomized controlled trials remain controversial and do not fully reflect the specific effects of albumin treatment." (PMID 39101009, 2024). "However, we also have to note that albumin replacement in addition to crystalloids will not improve the rate of survival in patients with severe sepsis." (PMID 39055134, 2024). "Notably, in our cohort, we demonstrated that the predictive value of CRP/albumin-based markers is independent of sepsis, which inherently induces strong elevations of CRP and a marked decline in albumin due to leakage into the extracellular fluid." (PMID 39385197, 2024). "However, Bou Chebl's study noted that in patients with sepsis, the AUROC of LAR was greater than that of lactate but smaller than that of albumin, and that all three indices had ROC curves close to the reference line when examining septic shock patients separately (p > 0.05)." (PMID 39246646, 2024). "CC also reversed the melatonin-induced decrease of the sepsis score in CLP mice and blocked the protective effect of melatonin on blood biochemical and blood routine parameters, as evidenced by increased RBC and decreased ALB, LYM, MON, GRA, and PLT in the MEL+CC+CLP group." (PMID 37101253, 2023).
Sepsis (continued). "Nevertheless, a meta-analysis revealed no significant efficacy of human albumin in sepsis patients, which may be attributed to several included studies with “high-risk-of-bias”." (PMID 37089426, 2023). "However, the ALBIOS trial did not identify a significant benefit of albumin infusion in patients with sepsis." (PMID 37193993, 2023). "A pooled analysis of primary outcome mortality data of sepsis patients treated with human albumin in SAFE, ALBIOS, and EARSS studies, confirming that albumin treatment could dramatically decrease mortality in SS or sepsis patients." (PMID 37089426, 2023). "However, the available data on albumin at the time of ED admission and sepsis outcomes are scarce, and almost absent on infections more generally." (PMID 37240554, 2023). "Our data suggest that elevated aspartate aminotransferase and lactate dehydrogenase levels and low albumin levels when combined with other factors such as blood cell counts and triglyceride and ferritin levels can assist clinicians in evaluating HLH in children with sepsis." (PMID 37863910, 2023). "Albumin, a non-synthetic colloid, has been used over the years, with initial studies suggesting potential advantages over crystalloids in patients with severe sepsis." (PMID 37764075, 2023). "Albumin is a negative acute-phase reactant and its level decreases during injuries and sepsis." (PMID 37082727, 2023). "In addition, a post hoc subgroup analysis of septic shock patients showed a lower 90-day mortality in the albumin group, which was not the case for sepsis." (PMID 37764075, 2023). "Independent predictors, including age, gender, ethnicity, potassium, calcium, albumin, hemoglobin, alkaline phosphatase, vasopressor, Elixhauser score, respiratory failure, and LDH were identified and used to establish the nomogram (LDH-model) for predicting one-year mortality for sepsis patients." (PMID 37807068, 2023). "Serum albumin concentration may be affected by albumin infusion, dehydration, sepsis, trauma and liver disease, remaining independent of the nutritional status, yet it decreases in response to inflammation." (PMID 37239661, 2023). "In 2014, the Albumin Italian Outcome Sepsis (ALBIOS) study, a large multicenter open-label randomized controlled trial, showed that in patients with severe sepsis, resuscitation with 20% albumin and crystalloids did not improve survival compared to crystalloids alone." (PMID 37764075, 2023). "If albumin supplementation in patients could restore thiol levels with a consequent beneficial effect in patients with sepsis, is not yet demonstrated." (PMID 35624664, 2022). "However, in a randomized, multicentre, open-labeled trial of 1818 patients with severe sepsis, 20% albumin did not improve at the 28- and 90-day survival compared with crystal alone." (PMID 35931952, 2022). "In addition, it was demonstrated that preoperative serum albumin values in patients with postflexible URS sepsis are significantly lower than in patients without sepsis." (PMID 35464554, 2022). "Five of the 12 patients with worsening IAH were fluid overloaded, so diuretics, albumin and/or renal replacement therapy were instituted: IAP reduced in 1, who survived; 2 developed ACS and multiple organ failure and died, while 2 had persistent respiratory failure, sepsis and died." (PMID 35241135, 2022). "Thus, a lower AGR can result from a combination of low albumin and high globulin, and the combined biomarker might be a robust predictor of S-AKI in elderly sepsis patients." (PMID 36053443, 2022). "However, there has been no similar study on the correlation between ALB levels and death alone in sepsis patients with AKI undergoing CRRT." (PMID 35109818, 2022). "Overall, these results suggest the possibility that the activation of proteolytic enzymes might occur in the plasma of patients with sepsis and septic shock, therefore, the proteolytic activity upon CETPI could be generating peptides that eventually end up binding to albumin." (PMID 36536294, 2022).
Sepsis (continued). "Likewise, 35 types of lab tests, including albumin, globulin, and prothrombin time, showed significantly different distributions between sepsis and nonsepsis patients (P<.001)." (PMID 35704364, 2022). "Indeed, comparisons of albumin and crystals have been studied in critically ill patients, sepsis, septic shock, non-cardiac surgery, hemorrhagic shock, and stroke." (PMID 35694666, 2022). "First, the values of serum albumin or BUN may change over time, and this study only included the initial BAR value without monitoring its dynamic change, although these values may be more accurate in predicting the prognosis of sepsis." (PMID 36407534, 2022). "In summary, the levels of albumin or fibrinogen may be not effective prognosis factor in predicting sepsis-related mortality." (PMID 35990041, 2022). "The ratio of serum levels of CRP to albumin has been demonstrated to be a more accurate indicator than albumin and CRP levels alone for determining the prognosis of patients with various inflammatory diseases such as sepsis, cancer, acute pancreatitis, ulcerative colitis, and hepatitis B." (PMID 33453709, 2021). "While a positive correlation between biomarker levels and SOFA score may exist, this relationship does not seem to occur between albumin oxidation forms and sepsis severity scores when analyzing pooled patients." (PMID 34447316, 2021). "Although some of the antimicrobial therapy guidelines recommend special caution in situations with increased volume of distribution such as sepsis or septic shock, cystic fibrosis, severe burns or ascites, there are no special considerations based on ALB concentrations." (PMID 33672057, 2021). "Moreover, the presence of neutrophils enhances sepsis-increased albumin leak in HPMEC but not in HUVECs." (PMID 33725263, 2021). "IgM levels did not correlate with albumin (r = 0.058, p = 0.73), or immune markers TNFα (r = −0.027, p = 0.86), IL-1 (r = 0.1292, p = 0.91), IL-6 (r = −0.1615, p = 0.30), or IL-8 (r = −0.0209, p = 0.89) in the sepsis cohort." (PMID 34830673, 2021). "We found lower median albumin level among patient diagnosed with sepsis than non-sepsis." (PMID 35199783, 2021). "Not surprisingly, during sepsis a ROS storm may quantitatively alter the oxidation status of albumin leading to a decrease in HMA and an increase in HNA1 and HNA2." (PMID 34447316, 2021). "This study observed the changes of serum albumin (ALB), prealbumin (PAB), hemoglobin (Hb), C-reactive protein (CRP), immunoglobulin (IgG, IgA, and IgM), APACHE II score before and after treatment to evaluate the efficacy of alanyl glutamine in nutritional support therapy for patients with sepsis." (PMID 33725958, 2021). "In sepsis patients, SIRT1 negatively correlated with serum creatinine (Scr), white blood cells (WBC), C-reactive protein (CRP), acute physiology, and chronic health evaluation II (APACHE II) score, and sequential organ failure assessment (SOFA) score, while it positively correlated with albumin." (PMID 33263643, 2020). "Consequently, the ALBumin Italian Outcome Sepsis (ALBIOS) study investigated the possible impact on outcome of albumin administration and maintenance of serum albumin concentrations to at least 30 g/l in 1810 patients with severe sepsis and septic shock." (PMID 33287911, 2020). "The ALBIOS study, a large Italian randomized controlled trial, gave some suggestions on whether or not albumin administration improves outcomes in severe sepsis and septic shock." (PMID 32449147, 2020). "A univariate analysis indicated that age, serum albumin level, RDW value, APACHE II score, platelet count, serum creatinine level, presence of liver cirrhosis, and urine output <0.05 mL/kg/h the first day were significant predictors of mortality in sepsis-induced AKI patients undergoing CRRT." (PMID 30015549, 2018).
Sepsis (continued). "The level of albumin in this model was not measured or controlled however, and is something that warrants consideration in future studies, particularly with a view to approaching those seen in neonates with sepsis." (PMID 29691444, 2018). "There was, however, a nonsignificant trend in favor of albumin in patients with severe sepsis." (PMID 30374936, 2018). "When capillary pressure (or transendothelial pressure difference) is low, as in hypovolemia or sepsis and especially septic shock, or during hypotension (after induction and anaesthesia), albumin or plasma substitutes have no advantage over crystalloid infusions, since they all remain intravascular." (PMID 29789983, 2018). "In attempt to further investigate safety of dextran-70 as an alternative to albumin we propensity-score matched patients with severe sepsis or septic shock who received dextran-70 to those who did not receive dextran-70 in a cohort of patients treated in a single intensive care unit (ICU)." (PMID 28683810, 2017). "Furthermore, the presence or absence of albumin in these resuscitation fluids did not appear to modulate cfDNA concentrations during early sepsis." (PMID 28105603, 2017). "In addition to its plasma volume expanding activity, human serum albumin (HSA) has anti-oxidant and anti-inflammatory properties and may have a protective role in the microcirculation during sepsis." (PMID 26942605, 2016). "The following variables were significantly different between patients with and without ARC: age, body weight, body height, body mass index, BSA, APACHE II scores, admission categories of post-operative patients without sepsis and trauma, and serum albumin (all p < 0.05)." (PMID 27729984, 2016). "At inclusion, cases complicated with severe sepsis had significantly higher plasma sCD14, IL-10, NOx levels, higher proportion of moderate/massive ascites, lower serum albumin and more episodes of overall previous infection per patients than those non-severe sepsis cases." (PMID 27861595, 2016). "The potential beneficial effects of albumin administration may not be manifested in all patients with sepsis, but are likely to be more pronounced in certain subgroups (higher severity, greater inflammatory response)." (PMID 26942605, 2016). "Previous literature suggests that the lower neutrophil counts and albumin levels found in animals with aspiration and concurrent sepsis would have been accompanied by lower chemokine levels than animals after aspiration without sepsis." (PMID 26423575, 2015). "ALBIOS was an open-label, randomized, and controlled study in which a comparison was made of the efficacy of crystalloid saline without and with administration of 20% albumin solution in 100 intensive care units in Italy with a total of 1818 patients with severe sepsis and septic shock." (PMID 26136776, 2015). "Furthermore, to our knowledge, no meta-analysis has compared albumin with saline in severe sepsis patients up to now." (PMID 25499187, 2014). "Concentrations of albumin were not significantly different in bitches with or without sepsis." (PMID 25430894, 2014). "The optimal time to administer albumin to patients with sepsis has not yet been explored." (PMID 25474401, 2014). "However, the safety profile of albumin was not consistent between subgroups, with patients with traumatic brain injury having increased mortality and patients with sepsis having decreased mortality." (PMID 25394836, 2014). "The results presented here suggest that albumin could be clinically useful as an adjunctive marker for diagnosis of pyometra, but albumin does not seem to be as valuable as SAA in the detection of sepsis." (PMID 25430894, 2014). "Furthermore, as the most commonly used crystalloid, no study stressed the role of albumin when compared with saline in severe sepsis patients." (PMID 25499187, 2014). "Albumin concentrations decrease in sepsis and may be valuable as a negative prognostic biomarker for survival." (PMID 25430894, 2014).